RUNX1 (RUNX family transcription factor 1)
Diseases named in the same sentence as RUNX1 in open-access papers (continued):
Sharing a sentence is not in itself a finding about the gene and the disease.
breast cancer (continued). "This could be attributed to the fact that PIK3CA and RUNX1 mutations are commonly observed in luminal-type breast cancer; in the intrinsic subtype, CDH1-altered ILC exhibited a higher proportion of luminal-type cases." (PMID 39201647, 2024). "The association of RUNX1 with breast cancer metastasis has also been confirmed in other studies." (PMID 38282862, 2024). "Recent studies have determined that RUNX1 presents somatic mutations such as nonsense, frameshift, and missense mutations, leading to its dysfunction and playing a suppressive role in luminal subtype breast cancer with ER positivity." (PMID 37697370, 2023). "RUNX1 has also been shown to exert protection against epithelial-to-mesenchymal transition (EMT) by antagonizing the oncogenic effects of YAP1—a transcription co-factor implicated in breast cancer metastasis." (PMID 36831308, 2023). "RUNX1 mutations are closely related to tumorigenesis in leukemia and breast cancer." (PMID 35534796, 2022). "Genes that annotate to enhancer regions (cluster 3) are enriched with signaling pathways of validated estrogen networks and include several estrogen-related pathways in addition to transcriptional regulation by RUNX1, a pathway linked to breast cancer and tumor suppression." (PMID 35862394, 2022). "For example, RUNX1 has been shown to regulate the estrogen receptor-positive luminal lineage, and RUNX1 mutations may present as an additional genetic predisposition in breast cancer development." (PMID 34485309, 2021). "Therefore, we analyzed the relationship between RUNX1 mutations and the infiltration of immune cells in breast cancer." (PMID 34485309, 2021). "This suggests that RUNX1 mutation may be used as a potential marker for detecting immune cell infiltration in breast cancer." (PMID 34485309, 2021). "Moreover, mutations in RUNX1 and CBFβ are associated with the ER+ sub-type of breast cancer and is therefore predicted to have a tumour suppressor role in this context." (PMID 32005976, 2020). "Further in-silico or functional analysis should be carried out to further investigate the effect of the identified SNP to ALCAM and RUNX1 gene as well as the crosstalk in between germline variations and somatic mutations in these breast cancer-associated genes." (PMID 31757997, 2019). "Importantly, RUNX1 somatic mutations were found in ER+, luminal subtype of breast cancer and indicate a tumor suppressor role for RUNX151,52." (PMID 31757997, 2019). "RUNX1 is implicated in proliferation control of breast cancer." (PMID 29485617, 2018). "Genetic studies show Runx1 is mutated in 5% of Luminal A subtype breast cancer patients." (PMID 28407681, 2017). "The results identified that Runx1 expression is associated with breast cancer stages and subtypes." (PMID 28407681, 2017). "The tumour suppressor RUNX1 is often lost or mutated in oestrogen receptor-positive breast cancers." (PMID 26916619, 2016). "The loss of RUNX1 from intestinal epithelial cells significantly induced tumorigenesis in a conditional knockout mouse model, and the knockdown of RUNX1 in breast cancer cells resulted in hyperproliferation and abnormal morphogenesis." (PMID 26984280, 2016). "Instead, E2-mediated AXIN1 suppression upon RUNX1 loss may contribute to ER+ breast cancer progression through mitotic aberrations that promote expansion of a stem cell-like population." (PMID 26916619, 2016).
breast cancer (continued). "Furthermore, we present evidence that deregulation of β-catenin in RUNX1-deficient ER+ breast cancer cells is associated with compromised mitotic checkpoint control, accelerated cell proliferation and increased expression of stem cell markers." (PMID 26916619, 2016). "Recurrent mutations of Runx1 have been detected in breast cancer, suggesting that aberrations in Runx-mediated cell differentiation may drive the development of this malignancy." (PMID 26030000, 2015). "Loss of RUNX1 may contribute to the development ofER+ luminal breast cancer under a background of eitherTP53 or RB1 loss and upon cooperation with otheradditional oncogenic events." (PMID 25415051, 2014). "We hypothesized that additional genetic events mightbe needed to cooperate with RUNX1-loss to promote the development ofluminal breast cancer from ER+ luminal MECs." (PMID 25415051, 2014). "The tumorsuppressor role of RUNX1 is also consistent with a previous observation in whichRUNX1 was found among a 17-gene signature associated with metastasisas a gene downregulated in metastasis-prone solid tumors, including breast cancer." (PMID 25415051, 2014). "Therefore, loss of Runx1 normal activities in tumor tissues may serve as an indicator of poor prognosis for breast cancer patients as revealed in several clinical studies." (PMID 28407681, 2017). "Additionally it has been shown that loss of function RUNX1 somatic mutations occur at a higher rate in estrogen receptor (ER) positive breast cancers, rather than ER negative breast cancers, further linking this TF to tumor suppressor activity in hormone receptor (HR) positive breast cancers." (PMID 40614729, 2025). "It has been reported that RUNX1 intron transcript 1 (RUNX1-it1) is significantly overexpressed in breast cancer tissues, and it can block the impact of ferroptosis by increasing GPX4 expression, thereby promoting the occurrence of breast cancer." (PMID 40009842, 2025). "Recently, RUNX1 and CBFβ have all garnered attention as potential clinical targets in breast cancer." (PMID 40614729, 2025). "A follow-up study supported the idea that RUNX1 mainly acts as a tumor suppressor in ER+ breast cancer, and it can exert oncogenic effects by suppressing the estrogen-mediated inhibition of AXIN1 and activation of the Wnt/β-catenin signaling pathway." (PMID 38430423, 2024). "In breast cancer, RUNX1 critically influences both the EMT and stemness, both of which are robustly linked to invasive tumor characteristics." (PMID 38430423, 2024). "Its expression is lost during the development of ER+ breast cancer, suggesting the tumor-suppressive role of RUNX1." (PMID 38430423, 2024). "In a tumor derived from human breast cancer stem cells grown in a mouse mammary fat pad, the expression of RUNX1 inhibits and the expression of RUNX2 and vimentin enhances the tumor growth." (PMID 38630262, 2024). "Upregulated RUNX1 inhibits the invasiveness of most breast cancer subtypes, especially in the early stages of tumorigenesis, and prevents the epithelial–mesenchymal transition in breast cancer cells." (PMID 39272372, 2024). "In breast cancer, RUNX1 significantly influenced these cellular processes, enhancing tumor invasiveness." (PMID 39309442, 2024). "Further investigations have solidified RUNX1's predominantly tumor-suppressive capacity in ER+ breast cancer by counterbalancing the estrogen-driven suppression of AXIN1, an integral component of the Wnt/β-catenin signaling pathway." (PMID 39309442, 2024). "Remarkably, cumulative evidence supports the concept that the role of RUNX1 in breast cancer depends on the hormone receptor context." (PMID 36766786, 2023).
breast cancer (continued). "In mouse-derived mammary tumors, as well as in the MDA-MB-231 TN cell line, loss of RUNX1 was shown to reduce cell proliferation, migration and invasion." (PMID 36831308, 2023). "In human breast cancer, RUNX1 activity is still a matter of debate and little is known about its role in tumor progression." (PMID 36766786, 2023). "The nuclear CBFB/RUNX1 complex transcriptionally represses the oncogenic NOTCH signalling pathway in breast cancer." (PMID 37187521, 2023). "Underpinning this phenotype, it has been suggested that RUNX1 binds directly to various proteins regulating transcription of genes involved in the control of mammary tumor promotion, such as FOXP3, GJA1 and RSPO3." (PMID 36831308, 2023). "RUNX1 expression was noted to be significantly high in some cases of the more invasive subtypes of breast cancer." (PMID 36831308, 2023). "Studies analyzing tissue microarrays (TMA) from TN breast cancer patients have correlated elevated RUNX1 expression to poor survival outcome." (PMID 36831308, 2023). "RUNX3 was part of a poor prognostic stromal gene signature in breast cancer patients, and very recently, RUNX1 (and also RUNX2) was identified through an epigenetic analysis of murine mammary tumors to be highly upregulated in cancer-associated fibroblasts." (PMID 36831308, 2023). "In many solid tumors, including colon, ovarian, and breast cancers, the expression level of RUNX1 is significantly increased compared to paracancerous tissue." (PMID 36429115, 2022). "According to the result of TF analysis, although most of the TFs have been reported to be associated with breast cancer, there were still TFs such as EOMES, POU3F2, NR3C1, and RUNX1 that were less reported in breast cancer." (PMID 36313438, 2022). "On the one hand, tumor suppressor capabilities of RUNX1 have been observed at the mRNA and protein levels in ER+ and/or PR+ breast cancers." (PMID 35867729, 2022). "Depletion of RUNX2 had a stronger inhibitory effect on the proliferation of breast cancer cells than the suppression of RUNX1 or RUNX3." (PMID 35534547, 2022). "Nevertheless, the role of RUNX1 in breast cancer appears to be more ambiguous and hormone-dependent." (PMID 35867729, 2022). "EBF1 is only deregulated in lung cancer, but only in two of the ten datasets, while RUNX1 is deregulated in lung cancer and breast cancer, but its regulation varies: it is positive in some datasets and negative in others of the same type of cancer." (PMID 36101460, 2022). "RUNX1 is thought to have a role in breast cancer and endometrial cancer, and reduced levels of it creates an environment which supports tumor growth." (PMID 35428183, 2022). "The expression of the RUNX1 protein also increased with disease progression both in the TN tumor samples, and in a mouse model of breast cancer." (PMID 35867729, 2022). "Accordingly, transcriptome studies have reported RUNX1 mRNA upregulation in the TN breast carcinomas." (PMID 35867729, 2022). "There was a decreasing trend in RUNX1 transcriptional levels from stage one to stage four in breast cancer patients." (PMID 34485309, 2021). "In breast cancer, tsRNA‐19, tsRNA‐29, tsRNA‐46, and tsRNA‐112 selectively respond to the expression of RUNX1 tumor suppressor." (PMID 33332661, 2021). "We found that the methylation level of RUNX3 in breast cancer is completely opposite to that of RUNX1 and RUNX2." (PMID 34485309, 2021). "An increasing number of alterations have been identified in multiple tumor suppressor or activator genes in breast cancer patients, among which the RUNX1 gene has a high frequency of alterations." (PMID 34485309, 2021). "We analyzed the differentially expressed genes that were correlated with RUNX1 in breast cancer using LinkedOmics." (PMID 34485309, 2021). "RUNX1, as an oncogene and anti-oncogene, has also received increasing attention in many solid tumors including breast cancer, gastric cancer and colorectal cancer." (PMID 33937021, 2021).
breast cancer (continued). "The results showed that RUNX1 mutations significantly increased the levels of CD8+T cells, CD4+T cells, and macrophage infiltration in breast cancer." (PMID 34485309, 2021). "We performed UALCAN analysis to evaluate RUNX1 promoter methylation levels and its relationship with breast cancer patient characteristics." (PMID 34485309, 2021). "We found that ts‐112 and RUNX1 are correlated in normal breast epithelium and breast cancer cell lines, which is consistent with the tumor‐related activity of ts‐112 and the tumor suppressor activity of RUNX1." (PMID 33332661, 2021). "There was also a significant difference in RUNX1 levels between different breast cancer subclasses, with luminal type having the highest level and triple-negative showing the lowest level." (PMID 34485309, 2021). "In our study, RUNX1 showed two alternate terminator (AT) events in breast cancer, and one showed favorable prognosis while another showed unfavorable prognosis." (PMID 34834420, 2021). "An abnormal elevation of RUNX1 has been reported in various cancers, for instance, breast cancer, colorectal cancer, pancreatic cancer, and brain cancer." (PMID 34376784, 2021). "First, for some recurrent mutations, such as those from CTNNB1, CSF1R, JAK2, HRAS, and RUNX1, an exhaustive literature search showed that the clinical significance in breast carcinoma has rarely been addressed." (PMID 34203389, 2021). "Disruption of RUNX1 DNA binding by interfering with the RUNX1-CBFβ interaction leads to the epithelial-to-mesenchymal transition, a key event in breast cancer onset." (PMID 32655837, 2020). "RUNX1 suppresses breast cancer growth by repressing the activity of breast cancer stem cells and inhibiting ZEB1 expression directly." (PMID 32498288, 2020). "To date, the effect of RUNX1 phosphorylation on tumorigenesis and the clinical treatment of RUNX1 on breast cancer bone metastasis are uncertain." (PMID 32549768, 2020). "Here, we find that PAK4 phosphorylates RUNX1, which upregulates downstream genes related to osteoclast differentiation and maturation, including Jagged-1,IL-1α,IL-1β,IL-6 and PTHrP in breast cancer cells." (PMID 32549768, 2020). "Mechanistically, it will be interesting to determine if RUNX1-bookmarked lncRNAs have G1-specific roles in maintaining the normal mammary epithelial phenotype and/or in the onset and progression of breast cancer." (PMID 32655837, 2020). "Conversely, reduced expression of Runx1 in breast cancer cells leads to elevated expression of both pre-miR-378 and PPARGC1B, which is a host gene of miR-378, to create a FBL on that reduces cell migration and invasion." (PMID 32102656, 2020). "Functionally, we demonstrate that RUNX1 phosphorylation promotes osteolytic bone maturation and ERα-positive breast cancer-induced osteolytic bone damage in the mouse model of orthotopic breast cancer bone metastasis." (PMID 32549768, 2020). "There are more and more evidences showing that Runx1 inhibited the invasiveness of most kinds of breast cancer, especially in the early stage of tumor development." (PMID 32952599, 2020). "Together, these results indicate that RUNX1 phosphorylation at T207 modulates ER positive breast cancer cells bone-specific metastatic potential." (PMID 32549768, 2020). "Here, we found that PAK4 promotes ERα-positive breast cancer-induced osteolytic bone destruction by phosphorylating RUNX1." (PMID 32549768, 2020). "Our study confirms that in ERα positive breast cancer, RUNX1 phosphorylation involving in osteolytic bone destruction." (PMID 32549768, 2020). "Using human breast tumor microarray, we found that CBFB and RUNX1 levels were significantly lower in breast cancer tissues compared to normal breast tissues while NOTCH3 levels were the opposite." (PMID 31061501, 2019). "RUNX1 transcription factors on the other hand are tumor-suppressors in breast cancer, and their expression is decreased in aggressive types of breast cancer." (PMID 31281796, 2019).
breast cancer (continued). "Several lines of evidence support the notion that CBFB and RUNX1 are tumor suppressors in breast cancer." (PMID 31061501, 2019). "Recurrent mutations in RUNX1 and hyper methylation of RUNX3 locus have recently been discovered in breast cancer indicating tumor suppressor role of RUNX1 and RUNX3." (PMID 29581836, 2018). "Runx1 is also expressed in breast cancer samples including ductal carcinoma in situ and invasive ductal carcinoma." (PMID 28407681, 2017). "Runx1 was found to be under-expressed in several breast cancer subtypes, including Luminal B, Her2 enriched and basal like breast cancers, which all have a poor prognosis." (PMID 28407681, 2017). "It has been shown that miR27a, miR144 and miR387, which are upregulated during breast cancer progression, are directly down-regulating Runx1." (PMID 28407681, 2017). "For example, while Runx1 has been shown to function as a tumor suppressor in prostate cancer, it acts as an oncogene in ovarian cancer and in a mouse model of breast cancer." (PMID 28407681, 2017). "Runx1 involvement in breast cancer was first tested using a panel of normal and breast cancer cell lines representing different breast cancer subtypes." (PMID 28407681, 2017). "We have shown by multiple lines of evidence that down-regulation of Runx1 is a key step during breast cancer EMT." (PMID 28407681, 2017). "To further establish a definitive role for Runx1 function in preserving the epithelial phenotype, we carried out a “rescue” study to examine the consequences of restoring Runx1 expression in mesenchymal like breast cancer cells." (PMID 28407681, 2017). "Here we focused our study on normal mammary epithelial and epithelial like breast cancer cells, and discovered a key function for Runx1 in preventing EMT." (PMID 28407681, 2017). "The central genes of the network (RUNX1, PAX3, GATA4 and DLX5) were subjected for epigenetically dysregulation in association with different breast cancer subtypes." (PMID 28747748, 2017). "We therefore have focused our studies on the functional activities of Runx1 in basal subtype breast cancer cells." (PMID 28407681, 2017). "TCGA data show that Runx1 is expressed at the lowest level in patients with basal like breast cancer." (PMID 28407681, 2017). "The loss of epithelial morphology in normal-like mammary cells by knockdown of Runx1 raises a compelling question regarding the role of Runx1 in breast cancer cells." (PMID 28407681, 2017). "With a highly specific Runx1 antibody, we applied immunohistochemistry to determine the expression pattern of Runx1 in different types of breast cancer using a Tissue Microarray (TMA) of 185 tumors and 6 control normal adjacent tissue sections." (PMID 28407681, 2017). "The central genes of the network were identified and RUNX1, PAX3, GATA4 and DLX5 genes were subjected for epigenetically dysregulation in association with diversity of breast cancer subtypes." (PMID 28747748, 2017). "Particularly, Runx1 has been identified as a significant controller of tumorigenesis in various epithelial cancers; however, its contribution in breast cancer development is still under debate." (PMID 26735887, 2016). "In an oncogenic context, physical interaction of FOXP3 with the transcription factor RUNX1 has been shown to regulate the expression of breast cancer related genes." (PMID 27588474, 2016). "Both of them represent the ER+ luminal A breast cancer subtype, in which RUNX1 is most highly expressed, attributable in part to promoter hypomethylation." (PMID 26916619, 2016). "Taken together, our results assign a role for RUNX1 in antagonizing oestrogen-mediated AXIN1 suppression and highlight AXIN1 as a potential target for the treatment of RUNX1-deficient ER+ breast cancer." (PMID 26916619, 2016).